CD4 (CD4 molecule)
Diseases named in the same sentence as CD4 in open-access papers (continued):
Sharing a sentence is not in itself a finding about the gene and the disease.
cancer (continued). "Here we demonstrate for the first time in a cancer setting, the generation of inducible TReg cells from CD4+CD25- T cells where a subset produce IFNγ in vitro." (PMID 22666318, 2012). "For each kind of cancer, a significant proportion of the patients had their Treg/lymphocyte > 3 % and Treg/CD4+ > 10 % or >15 %, respectively." (PMID 22722448, 2012). "Recent studies revealed that CD4+ T-cells and macrophages are required in the clearance of senescent cells, which is critical to the prevention and regression of cancers." (PMID 22479575, 2012). "The potentimmunosuppressive effects of CD4+CD25+ Tregsmay in part explain the failure of many immunotherapeutic approaches to cancer." (PMID 22802961, 2012). "The capacity of CD40-activated B cell-based cancer vaccine to induce CD4+ and CD8+ T cell responses also has been shown in vivo in mice and a large animal model in dogs." (PMID 22592077, 2012). "PD-L1, the ligand of PD-1, is expressed on cancer cells and is involved in negative regulation of immune responses, as they increase apoptosis of T-cells and inhibit CD4 and CD8 T-cell activation." (PMID 23234250, 2012). "An important finding in our study is the downregulationof β-2AR in cancer patients' lymphocytes.We have demonstrated decreased levels of β-2ARexpression on CD4+IFN-γ+ and CD4+IL-17+ lymphocytesin patients' PBMCs and TILs." (PMID 23507624, 2012). "Currently, we have initiated a large cohort multi-center observation regarding the modulatory efficacy of this novel strategy on the CD4+CD25+highFoxp3+ Tregs in malignancies." (PMID 22722448, 2012). "In conclusion, we describe the presence of naturally occurring IDO-specific CD4+ T-helper cells in cancer patients and in healthy donors." (PMID 22539948, 2012). "Compared to pretreatment levels, cancer patients have significantly increased average number of CD4+ T cells after 7 days of sunitinib treatment (3.17±0.92×105 to 3.63±0.84×105; paired t-test, p = 0.04)." (PMID 22761653, 2012). "The selective uptake of GalNAc-glycosylated antigens (Tn-antigens) by the common human and murine dendritic cell (DC) C-type lectin MGL, makes it possible to induce cancer specific glycopeptide antibodies in mice and man through induction of a CD4+ Th cells." (PMID 23189185, 2012). "IDO is spontaneously recognized by HLA class II-restricted, CD4+ T cells in cancer patients and in healthy individuals." (PMID 22539948, 2012). "For example, cancer patients treated with IL-7 experienced marked increases in peripheral CD4+ and CD8+ T cells, resulting in a rejuvenated circulating T-cell profile." (PMID 22369276, 2012). "Immunity to cancers, allogenic transplantations and autoimmune disorders thus requires CD4+ T cells for optimal priming, maintenance and memory responses." (PMID 23071696, 2012). "We demonstrated the presence of naturally occurring IDO-specific CD4+ T cells in cancer patients and to a lesser extent in healthy donors by cytokine release ELISPOT." (PMID 22539948, 2012). "In the lobular histological type, there is a lower lymphocytic infiltration than in ductal cancers, particularly regarding CD4+ and FOXP3+ cells." (PMID 22471961, 2012). "Our findings support further use of CD4 T cell depletion therapy for inducing long-lived immunity to cancer." (PMID 22046294, 2011). "We were unable to find any association between CD4, CD8 or Foxp3+ (presumed Tregs) and cancer recurrence or with other clinico-pathological variables." (PMID 21864372, 2011). "Some seronegative cancer patients and healthy donors showed multiple epitope-specific CD4+ T cell responses, as seen in seropositive cancer patients." (PMID 21858191, 2011).
cancer (continued). "Natural Treg cells have been described as CD4+CD25+ T cells in mice, and initial reports in cancer patients relied solely on the assessment of CD4 and CD25 expression for the identification of Treg cells." (PMID 21904560, 2011). "When looking at the NADM group, at the time of cancer diagnosis, median CD4 count was 352 cells/mm3 and 51.1% (n = 23) of the patients had undetectable viral loads (< 50 copies/ml)." (PMID 21443771, 2011). "Accordingly, increased numbers of cancer-infiltrating CD4+ and CD8+ T cells correlated well with improved prognosis of PC patients." (PMID 22110523, 2011). "In this study, we have addressed the presence and distribution of CD4+ T cells specific for the tumor antigen ESO, of the cancer/testis group, within circulating CD4+ T-cell subsets of EOC patients." (PMID 21829534, 2011). "We and others have reported increased frequencies of CD4+CD25highFOXP3+ Treg cells in cancer patients." (PMID 21904560, 2011). "The expansion of naïve Treg cells was apparent as part of the Treg-cell pool as well as in relation to the total number of CD4+ T cells in cancer patients." (PMID 21904560, 2011). "CD8+ T cell expansion has been reported to occur when these cells are exposed to increased IL-2 levels or during adoptive cancer immunotherapy using antigen-specific CD8+ T cells in the presence of IL-2-sufficient CD4+ T cells." (PMID 21423804, 2011). "This lack of requirement for T cell help appears somewhat contradictory to reports that CD4 help plays a major role in effective CD8 T cell responses to cancer." (PMID 22046294, 2011). "Analyses of NY-ESO-1-specific spontaneous immune responses in cancer patients revealed that antibody and both CD4+ and CD8+ T cell responses were induced together in cancer patients." (PMID 21858191, 2011). "In considering anti-CD4 therapy for patients with cancer, the balance between CD4 T cell help and suppression must be considered." (PMID 22046294, 2011). "Regulatory T cells (Treg) are CD25hi Foxp3+ CD4+ T cells that have been involved in the failure of the immune system to control the development of numerous cancers both in humans and in mice." (PMID 24212964, 2011). "TMV secreted by cancer cells can convert CD4(+)CD25(–) T cells into CD4(+)CD25(+)FOXP3(+) Treg, while increasing the expression by these cells of immune-suppressive factors, such as FasL, IL-10, TGF-β1, CTLA-4, granzyme B, and perforin." (PMID 22046194, 2011). "Although CD8 cytotoxic T lymphocytes are believed to have a major role in eradicating cancer, CD4 helper T lymphocytes are likely to have a critical role in immunotherapy since they participate in generation and persistence of CD8 T-cell responses." (PMID 22053850, 2011). "In conclusion this study demonstrates that CD4+CD127lowFOXP3+ Treg cells are increased in cancer patients." (PMID 21904560, 2011). "Of interest, filgrastim has been reported to increase the frequency of CD4+CD25high Treg cells only when given to cancer patients in combination with cyclophosphamide as HSC mobilization regimen." (PMID 21062439, 2010). "In support of this idea, it has already been shown that antitumor immunity in cancer patients is enhanced by the elimination of Tregs and an over-abundance of tissue CD4 Tregs leads to additional dysfunctions in antigen-specific CD8 T cell responses." (PMID 20946663, 2010). "For example, elevated proportions of CD4+CD25highFOXP3+ Treg in PBMC of cancer patients have been reported, and accumulations of Treg in the tumor microenvironment are associated with reduced patient survival." (PMID 20661468, 2010).
cancer (continued). "We have studied Treg cells in cancer in experimental mice that express naturally selected, polyclonal repertoire of CD4+ T cells and which preserve the heterogeneity of the Treg population." (PMID 21049016, 2010). "The frequency and suppressor functions of peripheral blood CD4+CD25highFOXP3+ Treg are higher in patients with cancer than normal controls." (PMID 20661468, 2010). "There is evidence of increased apoptosis among CD4+ T cells in peripheral blood lymphocytes from cancer patients and animal models." (PMID 19812686, 2009). "For cancer vaccination, the goal is to generate antigen-loaded DCs that efficiently stimulate robust and long-lasting CD4+ and CD8+ T cell responses in the patient with cancer, with the emphasis on “long-lasting”." (PMID 20182533, 2009). "Presence of epitopes of infectious agents and cancer antigens with dual specificity for both CD4+ and CD8+ T cell subsets has previously been reported by us and others." (PMID 19901990, 2009). "Although FoxP3 is still regarded as the most reliable marker of Tregs in human cancer, it can also be expressed by epithelial tumor cells and in vitro activated CD4+ and CD8+ T cells." (PMID 19641607, 2009). "Using the peptide, we established a suitable protocol for the propagation of MAGE-A4-specific CD4+ T cells applicable to adoptive Th1-cell therapy of human cancer." (PMID 19277034, 2009). "This study reports ahigher frequency of HPV16-specific CD4+ T-cell responses in patients withcervical carcinoma than in women with CIN III lesions." (PMID 18288269, 2007). "Previous studies have demonstrated that activation of CD4+ T cells is required for immunisation of CD8+ T cells against cancer." (PMID 16421594, 2006). "The group that exhibited both highCD8+ and high CD4+ T-cell infiltration in cancer stroma demonstrated significantly higher survival rates than the rest of the patients (log-rank test, P=0.006)." (PMID 16421594, 2006). "The number of infiltrating CD8+ or CD4+ T cells in cancer stroma was overwhelmingly higher than that within cancer nests." (PMID 16421594, 2006). "The results indicated that high-CD8+/high-CD4+ T cells infiltration in cancer stroma was an independent favourable prognostic factor (risk ratio, 3.221; P=0.0092)." (PMID 16421594, 2006). "After chemotherapy there was simultaneous accumulation of all subsets in cancer patients, resulting in rapid restitution of CD4+ T-cell counts within 3 months." (PMID 15642146, 2005). "A higher proportion of CD4+CD25+ TR cells was found in peripheral blood of cancer patients and to be related to poor prognosis of the diseases." (PMID 15679891, 2005). "In order to compare thymic activity after lymphodepletion, we measured TRECs longitudinally in CD4+ T-cells in the same RA and cancer patient cohorts." (PMID 15642146, 2005). "CD4 reactivity was found to be far more common among the group of normal donors than the cancer patients, again suggesting that HPV16-specific CD4+ T-cell immunity is important for disease protection." (PMID 15986031, 2005). "T cell-mediated cancer immunotherapy is dose dependent and optimally requires participation of antigen-specific CD4+ and CD8+ T cells." (PMID 15566571, 2004). "Of the total cancer cases, 51.1% (23 out of 45) were recognised as possessing high CD4+ T cell infiltration." (PMID 14583778, 2003). "Large numbers of lymphocytes were seen in inflamed and malignant pancreas, where CD4+CD103- T cells form the predominant subset." (PMID 12434297, 2002). "T cell dysfunction, a hallmark of chronic infection and cancer where antigens persist without adequate costimulation and CD4 T cell help, arises through multiple mechanisms." (PMID 41315764, 2026). "Further immune cell infiltration analysis revealed that cancer-associated fibroblasts (XCELL), CD4+ T cells (TIMER), uncharacterized cells (QUANTISEQ), CD8+ T cells (EPIC), as well as M2 macrophages and resting mast cells (CIBERSORT) were positively correlated with the risk score." (PMID 41602418, 2026).
cancer (continued). "The increased risk of cancer following KS may reflect HIV-associated immunosuppression, which is linked with uncontrolled HIV and low CD4 counts." (PMID 41546776, 2026). "CD4 CTL can potentiate direct cancer killing in numerous settings." (PMID 41542042, 2026). "Furthermore, both human and murine models of cancer have demonstrated the existence of idiotype-specific CD4+ T-cell populations that recognize idiotype fragments presented on HLA-II molecules by antigen-presenting cells." (PMID 40391216, 2025). "The inhibition of CD4+ T lymphocytes was also reported by cancer-derived exosomes." (PMID 41294803, 2025). "Treg cells can also develop from naive CD4+ T cells in the exposure of cancer-derived exosomes." (PMID 40407494, 2025). "Moreover, exposure of CD4+ T-cells to immunosuppressive supernatant of cancer cells resulted in lower JAK-STAT1/2 and NFκB STP activity." (PMID 39996782, 2025). "In cancer, CD4+ T cells may improve immunity by releasing effector cytokines such as interferon-gamma (IFNγ) and tumour necrosis factor alpha (TNFα), and assisting cytotoxic and antibody responses." (PMID 40560407, 2025). "The role of the CD4+/CD8+ ratio as a predictor in cancers is disputed by the existing evidence." (PMID 40171262, 2025). "IL2, predominantly released by antigen-activated CD4 + T cells, is pivotal in cancer immunotherapy." (PMID 41246353, 2025). "Conversely, NADC patients often had suppressed viral load (<50 copies/mL) and CD4+ counts >500/μL, suggesting these cancers may develop independently of severe immunosuppression." (PMID 41003137, 2025). "Given the importance of establishing the memory feature in cancer immunotherapy that provides long-term treatment benefits, we examined the percentage of effector memory CD4+ (CD3+CD4+CD44+CD62L- cells) and CD8+ T cells (CD3+CD8+CD44+CD62L- cells) in splenocytes of treated mice." (PMID 40585984, 2025). "While effector CD8+ T cells activated by antigen-presenting cells have long been considered the primary immune target because of their unique cytotoxicity, several studies in recent years have identified cytotoxic CD4+ T cells with a cytotoxicity program that can directly kill cancer cells." (PMID 41230345, 2025). "Cancer vaccines utilize cancer-specific antigens to stimulate the immune system to counteract tumors by inducing a robust and long-lasting antigen-specific expansion of both CD4+ and CD8+ T cells." (PMID 40573922, 2025). "Additionally, we will enroll an HIV-negative cancer cohort and apply stricter inclusion criteria-such as matching CD4+ T cell counts, viral load levels, and antiretroviral therapy duration-to further refine the study design." (PMID 40927725, 2025). "In contrast, the ratio of CD8+ T cells to CD4+ T cells was significantly higher in the cancer core, supporting the hypothesis that CD8+ T cells specifically migrate to areas of high cancer density to execute their cytotoxic function." (PMID 39975273, 2025). "Subtypes of CD4+ T-cells and their Immunological Roles in Cancer." (PMID 40860882, 2025). "However, when we excluded PWH with severe immunosuppression (<200 CD4 cells/μL) in a sensitivity analysis, the association between HIV-1 viremia and cancer risk became stronger." (PMID 39736138, 2025). "In the two cases presented in this report, we observed that the integration of albuvirtide into existing antiretroviral regimens resulted in successful viral suppression, accompanied by CD4 + T cell count improvements despite concurrent immunosuppressive cancer therapy." (PMID 40251661, 2025). "Preclinical studies on nanoformulations for CD4+ T-Cell immunotherapy in cancer." (PMID 40860882, 2025). "Furthermore, HLA DR+ CD4+ T cells were significantly enriched in the peripheral blood of patients responding to immunotherapy in a pan-cancer study, demonstrating their potential for predicting immunotherapy responses." (PMID 40564200, 2025). "The results suggested that CD4 T cells expressing GZMA are of ability to anti-cancer." (PMID 40959273, 2025).
cancer (continued). "In GBM, we observed that both cancer cell antigen release (step 1) and immune cell trafficking to tumors (step 4)—including the recruitment of CD4 T cells, Th22 cells, monocytes, neutrophils, and eosinophils—were significantly upregulated in the high TMED9 expression group." (PMID 40124371, 2025). "However, more recent evidence shows that CD4+ T cells are essential for orchestrating an effective cancer immunotherapy response." (PMID 41249828, 2025). "Higher CD4 count consistently protected against post-cancer mortality and CCO." (PMID 41463249, 2025). "To address this, we developed UCPVax, a CD4+ Th1-inducing cancer vaccine." (PMID 40543509, 2025). "Meta-regression of TCM + ICIs vs. ICIs in cancer—CD4+T/CD8+T." (PMID 41244814, 2025). "GS levels were positively correlated with the infiltration fraction of several anti-cancer immune cells, including CD4+ memory T cells, dendritic cells (DCs), macrophage M1, and pro-cancerous T helper type 2 (Th2) cells, consistently in both the TCGA and GSE116918 cohorts (all p < 0.05)." (PMID 40710219, 2025). "However, MHC II molecules were recently found to be present on PDA cancer cells and can lead to CD4+ T-cell killing of cancer cells." (PMID 39941877, 2025). "CD4+ T cells are important effector immune cells alongside CD8+ T cells in cancer." (PMID 39782693, 2025). "The detailed functions of CD4+CTLs in CVIs and cancers have been discussed elsewhere." (PMID 41009359, 2025). "At the pan-cancer levels, pronounced increase in clonality among CD4+ TGF-β1+ T cells and CD8+ Temra cells in ICB-NRs could be seen based on their TCR clonality." (PMID 40054456, 2025). "Thus, future therapeutic cancer vaccines will likely benefit from stimulating B cells as well as T cells, which is what CD4-targeted vaccines provide." (PMID 40543509, 2025). "Additionally, CD4+ T helper cells contribute to anti-cancer immunity by enhancing the activity of CD8+ T cells and orchestrating the overall immune response through the production of signaling molecules called cytokines." (PMID 40951642, 2025). "Indeed, initial studies suggested that applying WBH at 41.8-42.2°C in patients with advance cancer, led to a reduction in CD4+ T-cells, accompanied by an increase in NK cells and γδ-T cells, which resulted in a decrease in the CD4+/CD8+ ratio." (PMID 40092992, 2025). "T regulatory (Treg) cells are a subset of CD4+ T cells that express the forkhead box P3 (Foxp3) transcription factor, promoting immune tolerance and preventing autoimmune reactions; however, their role can have paradoxical implications in cancer." (PMID 40951642, 2025). "Also, CD4 + T cell-rich tumors have been shown to be better therapies for immunotherapy and to correlate with better OS than CD4 + cell-depleted cancers." (PMID 41410866, 2025). "Their downregulation impairs antigen presentation to CD8+ and CD4+ T cells, promoting immune escape and compromising the effectiveness of T cell‐based immunotherapies, including checkpoint blockade, adoptive T cell therapy and cancer vaccines." (PMID 40673641, 2025). "Similarly, a recent study found that low baseline or nadir CD4 count and a CD4/CD8 ratio < 0.4 were strongly correlated with increased rates of infection-related cancers." (PMID 41295583, 2025). "Additionally, during activation, CD4+ T cells undergo less efficient metabolic reprogramming in aerobic glycolysis, similar to highly proliferative cancer cells." (PMID 39791749, 2025). "Additionally, the positive correlations between ADM and CD4+ T cells and macrophages were observed across the majority of cancer types, further supporting the potential role of ADM in immune regulation." (PMID 40529377, 2025). "Thus, visualizing the spatial distribution patterns of CD4+ cells by PET offers mechanistic insights into CD4-mediated therapy efficacy, with great potential for guiding combinatorial immunotherapies in patients with cancer." (PMID 40561008, 2025).